HSP90B1 (heat shock protein 90 beta family member 1)
Diseases named in the same sentence as HSP90B1 in open-access papers (continued):
Sharing a sentence is not in itself a finding about the gene and the disease.
bladder cancer (14 papers, 2015 to 2025). "Furthermore, to demonstrate the important role of HSP90B1 in bladder cancer chemotherapy, we analyzed the correlation between HSP90B1 and all chemotherapeutic agents in bladder cancer, and the results showed that HSP90B1 was strongly associated with cisplatin." (PMID 37433010, 2023). "In the present study, we demonstrated that HSP90B1 regulates p21 expression by enhancing the function of c-Myc through protein-protein interactions, and that increasing the expression of HSP90B1 can alleviate bladder cancer cell senescence caused by the knockdown of c-Myc." (PMID 37433010, 2023). "Furthermore, Heat shock protein 90 kDaβ1 (HSP90B1), a c-Myc-interacting gene, is strongly associated with cisplatin chemosensitivity in bladder cancer." (PMID 37433010, 2023). "Further studies showed that reducing HSP90B1 expression could alleviate the rapid growth and accelerate cellular senescence of bladder cancer cells caused by c-Myc overexpression, and that reducing HSP90B1 levels could also improve cisplatin sensitivity in bladder cancer cells." (PMID 37433010, 2023). "Previous research has indicated that miR-223-3p modulates the growth and aggressiveness of bladder cancer cells through HSP90B1." (PMID 41318560, 2025). "The authors demonstrated that HSP90B1 expression is significantly elevated in bladder cancer tissues compared to normal counterparts at both mRNA and protein levels." (PMID 41009692, 2025). "Previous studies have suggested that HSP90B1 is a promising candidate for cancer diagnosis and prognosis and plays a role in regulating cisplatin sensitivity in bladder cancer." (PMID 40823088, 2025). "The results indicated that HSP90B1 is highly expressed in multiple cancers, including bladder cancer (BLCA), prostate adenocarcinoma (PRAD), stomach adenocarcinoma (STAD), and kidney renal clear cell carcinoma (KIRC)." (PMID 39149033, 2024). "HSP90B1/c-Myc interaction regulates the p21 signaling pathway, which affects cisplatin chemosensitivity by modulating bladder cancer cell senescence." (PMID 37433010, 2023). "Among the c-Myc-interacting genes, HSP90B1 showed significantly differential expression in bladder cancer compared to its expression in corresponding normal tissues and showed the highest correlation with the cisplatin IC50 score." (PMID 37433010, 2023). "HSP90B1 interacts with c-Myc in bladder cancer and is involved in the regulation of bladder cancer cell senescence by c-Myc." (PMID 37433010, 2023). "In TCGA database bladder cancer samples, the mRNA expression of HSP90B1 and c-Myc mRNA expression were also significantly correlated." (PMID 37433010, 2023). "Our previous findings suggest that HSP90B1 is highly expressed in bladder cancer and can be used as a prognostic biomarker in patients with bladder cancer." (PMID 37433010, 2023). "CCK8 experiments showed that overexpression of c-Myc significantly enhanced the proliferation of bladder cancer cells (T24 and 5637), while knockdown of HSP90B1 reversed this result." (PMID 37433010, 2023). "In this study, the pseudo-time series analysis confirmed that the expression level of HSP90B1 was gradually increased during the progression of bladder cancer, indicating a poor prognosis." (PMID 36741702, 2022). "The results showed that the staining intensity of HSP90B1 protein in liver cancer, oesophageal cancer, colorectal cancer, and bladder cancer was higher than that in the corresponding normal tissues." (PMID 36291587, 2022). "Recent studies have reported that HSP90B1 can regulate the growth and invasion of bladder cancer cells; however, its role as a prognostic biomarker of BLCA remains unexplored." (PMID 36186448, 2022). "Heat shock proteins are widely reported as overexpressed in cancer and one study reported that HSP90B1 is overexpressed in canine bladder cancer." (PMID 28248271, 2015). "Taken together, these findings suggest that HSP90B1 may act as a pro-tumoral signaling and immune evasion molecule in bladder cancer." (PMID 41009692, 2025).
bladder cancer (continued). "The results of HSP90B1 gene enrichment analysis also showed that HSP90B1 was highly correlated with c-Myc and that HSP90B1 could regulate bladder cancer cell senescence in bladder cancer samples from TCGA database." (PMID 37433010, 2023). "To further analyze the relationship between HSP90B1 and c-Myc in bladder cancer, we analyzed the expression of HSP90B1 and c-Myc proteins in six bladder cancer samples selected by The Human Protein Atlas and found that HSP90B1 and c-Myc protein expression was significantly correlated." (PMID 37433010, 2023). "c-Myc and HSP90B1 expression were highly correlated in bladder cancer." (PMID 37433010, 2023). "In conclusion, our study demonstrated that HSP90B1 is involved in the regulation of the cellular senescence initiation gene p21 by c-Myc, a finding that provides new insights into improving cisplatin chemosensitivity in bladder cancer." (PMID 37433010, 2023). "Therefore, we suggest that HSP90B1 is involved in the regulation of bladder cancer cell senescence via its interaction with c-Myc." (PMID 37433010, 2023). "In addition, we found that overexpression of c-Myc significantly reduced the number of senescent cells in bladder cancer cells (T24 and 5637), while knockdown of HSP90B1 restored senescence in bladder cancer cells." (PMID 37433010, 2023). "Weighted gene co-expression network analysis (WGCNA), protein–protein interaction (PPI) network mutual analysis, and the Kaplan–Meier survival prognosis analysis were used to identify six key genes associated with the prognosis of bladder cancer: VEGFA, ANXA1, HSP90B1, PSMA7, PRDX6, and PPP1CB." (PMID 36741702, 2022). "Furthermore, recent studies report that the aberrant expression of HSP90B1 in lung adenocarcinoma, bladder cancer, colorectal cancer, and tongue squamous cell carcinoma is associated with a poor prognosis." (PMID 36291587, 2022). "Thus, among other genes that interact with c-Myc, we suggest that HSP90B1 plays an important role in cisplatin chemotherapy in bladder cancer and may be involved in the regulation of bladder cancer cell senescence by c-Myc." (PMID 37433010, 2023). "Additionally, HSP90B1 regulates the growth and invasiveness of bladder cancer cells." (PMID 37433010, 2023). "However, in our study, gene enrichment analysis showed that the ER stress gene HSP90B1 could affect apoptosis and cell cycle of bladder cancer cells." (PMID 36186448, 2022). "CDK4, KPNA2, PFDN5, HSP90B1, and ZNF121 were identified as prognostic differential genes in bladder cancer." (PMID 37433010, 2023). "According to BC values and the Kaplan–Meier survival curve, six genes related to the occurrence and development of bladder cancer were screened out: VEGFA, ANXA1, HSP90B1, PSMA7, PRDX6, and PPP1CB." (PMID 36741702, 2022). "The Kaplan–Meier survival prognosis analysis was performed on the top 100 genes, and 6 genes related to the survival prognosis of bladder cancer were finally screened out: VEGFA, ANXA1, HSP90B1, PSMA7, PRDX6, and PPP1CB." (PMID 36741702, 2022).
colorectal cancer (12 papers, 2011 to 2025). A primary or metastatic malignant neoplasm that affects the colon or rectum. "HSP90B1, delivered via exosomes from colorectal cancer cells, has been associated with poor prognosis in advanced colorectal cancer and contributes to liver metastasis by promoting the conversion of M1 to M2 macrophages." (PMID 40873588, 2025). "Two genes (FDXR and HSP90B1) are associated with cancer: FDXR with colorectal cancer and HSP90B1 with SCLC and mesothelioma." (PMID 21489244, 2011). "Additionally, an internalized antibody targeting cell surface HSP90B1 was also shown to effectively inhibit tumour angiogenesis in colorectal cancer." (PMID 36291587, 2022). "Additionally, HSP90B1 is speculated to be a factor that contributes to bad prognosis in many cancer types, including lung, oesophageal, gastric, and colorectal cancers." (PMID 36291587, 2022). "Studies reported that Heat Shock Protein 90 Beta Family Member 1 (HSP90B1), upregulated in many cancers, is a major contributor to evaluate the progression of carcinomas and may be a potential target for colorectal cancer therapy." (PMID 33997035, 2021).
glioblastoma (12 papers, 2015 to 2026). The most malignant astrocytic tumor (WHO grade IV). "Survival analysis revealed eight RBPs (PTRF, FNDC3B, SLC25A43, ZC3H12A, LRRFIP1, HSP90B1, HSPA5, and BNC2) are significantly associated with the survival of glioblastoma patients." (PMID 32272554, 2020).
osteosarcoma (12 papers, 2004 to 2025). A usually aggressive malignant bone-forming mesenchymal neoplasm, predominantly affecting adolescents and young adults. "Based on network pharmacology and transcriptomics, we identified ATP1A1, CLK1, SIGMAR1, PYGM, and HSP90B1 as the key targets of solasonine that influence the progression of osteosarcoma cells." (PMID 40831924, 2025). "For example, osteosarcoma shows a low level of oncogenic heat shock protein 90 kDa beta member 1 (HSP90B1), a member of the HSP90 family." (PMID 39759512, 2024). "In osteosarcoma, silencing HSP90B1 achieves tumor-suppressing effects on tumor growth, possibly through modulating the PI3K/AKT/mTOR pathway." (PMID 38711062, 2024). "The upregulation of miR-223-3p suppresses osteosarcoma cell proliferation and promotes apoptosis by downregulating HSP90B1." (PMID 39759512, 2024). "It is speculated that ATP1A1, CLK1, SIGMAR1, PYGM, and HSP90B1 may serve as therapeutic targets for solasonine in the treatment of osteosarcoma." (PMID 40831924, 2025). "Moreover, among our predicted targets, such as HSP90AA1, HSP90B1, which are related to the protein synthesis process, so we hypothesize that SS acts on the targets to regulate protein synthesis, which in turn affects the progression of osteosarcoma." (PMID 40831924, 2025). "In this study, five possible key targets of SS against osteosarcoma were finally identified: ATP1A1, CLK1, SIGMAR1, PYGM, and HSP90B1." (PMID 40831924, 2025). "HSP90B1 is a direct target of miR-223 and miR-223 may have a tumor suppressor function in osteosarcoma through the PI3K/Akt/mTOR pathway and could be used in anticancer therapies in osteosarcoma." (PMID 40831924, 2025).
ovarian carcinoma (11 papers, 2010 to 2025). A malignant neoplasm originating from the surface ovarian epithelium. "Release of multiple inflammatory cytokines into the plasma, including IFNγ, IL-1β, IL-6, IL-8, IL-10, TNFα, PlGF, and HSP90B1, is frequently associated with epithelial ovarian cancers (EOC)." (PMID 26858849, 2015).
diabetes (10 papers, 2010 to 2024). "Upstream regulator analysis suggested COMMD1, HIF1A, EGLN, PIK3R1 and MTORC1 as major upstream regulators for the phase shifts, while HSP90B1, YWHAZ, CNGA3, COL2A1 and TFRC were identified as the major upstream regulators for the amplitude changes observed in the diabetic retina." (PMID 38039846, 2024).
lung adenocarcinoma (9 papers, 2020 to 2025). A carcinoma that arises from the lung and is characterized by the presence of malignant glandular epithelial cells. "Relevant studies have shown that high expression of HSP90B1 usually predicts poor overall survival and disease-free survival of tumor patients, such as adrenal cortical carcinoma, renal papillary cell carcinoma, lung adenocarcinoma, and non-small cell lung cancer (NSCLC)." (PMID 36741702, 2022). "MiRNA hsa-mir-30a and lncRNA AC104472.1 constituted regulatory module for lung adenocarcinoma a with TPI1, KPNA2, MET, HSP90B1, P4HB, DSP, CDH1, and ENO1." (PMID 36138770, 2022).
prostate carcinoma (9 papers, 2012 to 2024). A carcinoma that arises from epithelial cells of the prostate gland. "Additionally, it has been shown that HSP90B1 induces apoptosis in prostate cancer cells, thereby preventing the cells from migrating." (PMID 36291587, 2022). "In Prostate cancer pathway, HSP90AB1 and HSP90B1 can indirectly affect cell proliferation and survival by activating Ar and thus binding to DNA sites." (PMID 38280998, 2024). "Five fusions (XPA-NCBP1, HARS2-ZMAT2, HSP90B1-DKFZp547P055, IL17RB-ACTR8, ANKRD23-ANKRD39) are shared between AML and prostate cancer." (PMID 23251452, 2012).
Obesity (8 papers, 2014 to 2024). Accumulation of substantial excess body fat. "In these studies mRNA expression of Hsp90ab1, Hsp90aa1, Hsp90b1, and TRAP1 were assessed from skeletal muscles of mice fed a high fat diet (diet-induced obesity, DIO) and compared to lean counterparts." (PMID 29434648, 2018). "miR-223 has been reported to associate with various types of diseases such as cancers, obesity, rheumatoid arthritis (RA) or cardiovascular diseases, via targeting tumour suppressor EPB41L3, targeting HSP90B1 or targeting cardiac troponin I-interacting kinase." (PMID 26893485, 2016).
leukemia (7 papers, 2014 to 2025). A malignant (clonal) hematologic disorder, involving hematopoietic stem cells and characterized by the presence of primitive or atypical myeloid or lymphoid cells in the bone marrow and the blood. "Several of the top 20 APL super enhancers are linked to genes known to have functional roles in leukemia, for example RNF216, FSCN1, FNDC3B, HSP90B1, C12orf75, and JARID2, among them, JARID2 is a hematopoietic tumor suppressor through recruiting PRC2 to repress self-renewal pathways." (PMID 41168841, 2025). "γ-Mangostin effectively suppresses leukemia cells by inducing ICD, which is characterized by increased expression of HSP90B1, ANXA1, and IL1B." (PMID 38627685, 2024).
nasopharyngeal carcinoma (6 papers, 2011 to 2025). A carcinoma arising from the nasopharyngeal epithelium. "In nasopharyngeal carcinoma, for example, the expression of hsp90b1 is closely associated with tumor proliferation, glycolysis and angiogenesis." (PMID 41155202, 2025). "Similarly, circADARB1 promotes radiotherapy resistance in nasopharyngeal carcinoma (NPC) by stabilizing SLC7A11/GPX4 through HSP90B1 upregulation." (PMID 40403492, 2025).
non-small cell lung carcinoma (6 papers, 2015 to 2024). A group of at least three distinct histological types of lung cancer, including non-small cell squamous cell carcinoma, adenocarcinoma, and large cell carcinoma. "Moreover, evidence highlighting the elevated expression of HSP90B1 in non-smokers diagnosed with non-small-cell lung cancer is detailed in Section 4.1.4." (PMID 38672772, 2024).
type 2 diabetes (6 papers, 2012 to 2024). "HSP90B1 gene expression was reduced in the hippocampus of a murine model of type 2 diabetes." (PMID 34685777, 2021). "However, experimental studies are required to reproduce these molecular consequences of HSF1 deficiency and to draw definitive conclusions about the causal relationship between the HSF1 gene, molecular chaperones HSP90B1, HSPA5, and FKBP4, and impaired proinsulin folding in type 2 diabetes." (PMID 36431071, 2022).
lymph node metastasis (5 papers, 2010 to 2024). "In addition, through correlation analysis of clinicopathological features, it was found that high level of HSP90B1 expression was positively correlated with lymph node metastasis and distant metastasis in patients." (PMID 38711062, 2024).
bipolar disorder (4 papers, 2009 to 2017). A disorder of the brain that causes unusual shifts in mood, energy, activity levels and the ability to carry out day-to-day tasks.
endometrial cancer (4 papers, 2016 to 2023). Primary or metastatic malignant neoplasm involving the endometrium (mucous membrane that lines the endometrial cavity). "Tumour protein D54 (TPD52L2) had a threefold higher concentration in endometrial cancer compared to controls while the molecular chaperone endoplasmin (HSP90B1) had a threefold lower concentration." (PMID 36807337, 2023). "Therefore, further studies on the downstream signaling pathways of HSP90B1 will improve our future understanding of the role and molecular mechanisms of HSP90B1 in PCOS-related cancer genesis such as endometrial cancer." (PMID 27846214, 2016).
Hepatic fibrosis (4 papers, 2022 to 2025). The presence of excessive fibrous connective tissue in the liver. "Research indicates that hepatitis C virus infection induces TGF-β1 secretion via HSP90B1 (GRP94)-mediated NF-κB activation, contributing to liver fibrosis pathogenesis." (PMID 41318560, 2025). "Studies have shown that Hsp90b1 is highly expressed in hepatic fibrosis; however, the specific role of Hsp90b1 in the context of silicosis remains unverified and warrants further investigation." (PMID 37833927, 2023). "In the past few years, studies have found that the expression of Hsp90b1 is upregulated in liver fibrosis, which is related to endoplasmic reticulum stress, and through proteomics and genetic investigations, Hsp90b1 has been identified as one of the biomarkers of hepatic fibrosis." (PMID 37833927, 2023).
liver disease (4 papers, 2015 to 2023). "Also, five proteins (HSP90B1, Protein S100-A9 [S100A9], MMP1, matrix metalloproteinase-9 [MMP9], and CSF3) in the IL17 signaling pathway are in phase III clinical trials for treating solid tumors and have the potential to treat liver diseases." (PMID 37209815, 2023).
oral cancer (4 papers, 2007 to 2024). "Clinical data from the TCGA database also indicated a significant correlation between HSP90B1 expression and T-stage, M-stage, and grading, aligning with findings by Chen, Feng & Chen (2022) in oral cancer." (PMID 38590708, 2024).
triple-negative breast carcinoma (4 papers, 2021 to 2025). An invasive breast carcinoma which is negative for expression of estrogen receptor (ER), progesterone receptor (PR), and human epidermal growth factor receptor 2 (HER2). "Furthermore, high expression of CNPY3 and HSP90B1 correlated with poor differentiation, PR negative status, triple-negative breast cancer (TNBC), a high Nottingham Prognostic Index (NPI), and an aggressive basal subtype." (PMID 41296387, 2025).
ulcerative colitis (4 papers, 2013 to 2025). An inflammatory bowel disease involving the mucosal surface of the large intestine and rectum. "Previous studies report a connection between HSP90B1 and various illnesses, including cancer, pneumonia, polycystic ovary syndrome, ulcerative colitis, and others." (PMID 36291587, 2022).
bladder urothelial carcinoma (3 papers, 2022 to 2025). "A recent study examining a pan-cancer perspective identifies HSP90B1 as a significant molecular chaperone involved in the progression of various malignancies, including bladder urothelial carcinoma." (PMID 41009692, 2025). "Importantly, high HSP90B1 expression in bladder urothelial carcinoma correlates with poor overall survival and disease-free survival, indicating its potential as a prognostic biomarker." (PMID 41009692, 2025).
sarcoma (3 papers, 2013 to 2022). A usually aggressive malignant neoplasm of the soft tissue or bone. "The investigation of the mutation driving mechanism revealed that the HSP90B1 gene alterations in UCEC were mostly missense mutations, while the sarcoma mutations were amplification mutations." (PMID 36291587, 2022).
astrocytoma (2 papers, 2013 to 2024). "In addition, the immunohistochemical results revealed that the staining intensity of HSP90B1 protein in patients with GBM was more pronounced than that in patients with astrocytoma or oligodendroglioma." (PMID 38665430, 2024).